UMOD (uromodulin)
Diseases named in the same sentence as UMOD in open-access papers (continued):
Sharing a sentence is not in itself a finding about the gene and the disease.
multiple myeloma (2 papers, 2022 to 2024). "We demonstrate that, indeed, the chain of events for PyV-haufen formation is similar to other forms of cast formation, such as myeloma casts or various cellular casts, that are all well-established biomarkers of intrarenal disease with uromodulin as a crucial building block." (PMID 38428993, 2024).
nephrocalcinosis (2 papers, 2017 to 2021). Nephrocalcinosis is a disorder that occurs when too much calcium is deposited in the kidneys. "Backcrossing 129 mice with B6N for up to seven generations restored CaOx crystal deposition and induced nephrocalcinosis, a process associated with uromodulin levels." (PMID 33968083, 2021).
nephronophthisis (2 papers, 2021 to 2022). Progressive tubulointerstitial injury, inherited in an autosomal recessive pattern, caused by mutations in genes involved in ciliary function, which may result in an end stage renal failure. "This can be the case with UMOD variants or CLCN5, usually associated with tubular dysfunction, or the mutations in type IV collagen genes and nephronophthisis genes." (PMID 35207681, 2022).
Obesity (2 papers, 2021 to 2025). Accumulation of substantial excess body fat. "UMOD, a kidney-specific protein typically abundant in urine, was also reduced in children with obesity." (PMID 39972214, 2025).
ovarian carcinoma (2 papers, 2006 to 2022). A malignant neoplasm originating from the surface ovarian epithelium. "The specific role of TCF2 methylation in the development and progression of ovarian cancer remains unknown, but TCF2 mutations are known to affect expression of downstream genes such as HNF4α, PKHD1 and UMOD." (PMID 16479257, 2006).
polycystic kidney and hepatic disease (2 papers, 2018 to 2021). "In most of the disease states, genes such as PKHD1 (polycystic kidney and hepatic disease 1) and UMOD (Uromodulin), two genes regulated by HNF1B have been found to be inactivated." (PMID 33580750, 2021).
proteinopathies (2 papers, 2023 to 2024). "Third, our work has broader implications, as TMED9-mediated entrapment of misfolded cargos likely causes many toxic proteinopathies, including uromodulin-associated kidney disease and retinitis pigmentosa, a form of blindness." (PMID 39303030, 2024).
rheumatoid arthritis (2 papers, 2014 to 2023). A chronic, systemic autoimmune disorder characterized by inflammation in the synovial membranes and articular surfaces. "Specific peptidic fragments were differentially excreted between groups; fragments of protein S100-A9 and gelsolin were less abundant in rheumatoid arthritis while fragments of uromodulin, complement C3 and fibrinogen were all increasingly excreted." (PMID 25144639, 2014).
Sepsis (2 papers, 2022 to 2025). Sepsis is defined as life-threatening organ dysfunction caused by a dysregulated host response to infection. "However, much work remains to be done to see if uromodulin is protective in the setting of sepsis and to determine its usefulness as a potential therapeutic." (PMID 35163625, 2022). "The kidney can also produce molecules that could potentially improve sepsis outcomes, such as erythropoietin, vitamin D and uromodulin." (PMID 35163625, 2022). "Interestingly, uromodulin expression in the kidney increases in the CLP model of sepsis, and initial imaging studies suggest there could be increased trafficking of uromodulin to the circulation." (PMID 35163625, 2022). "Finally, uromodulin, while extensively characterized as an immunomodulatory protein made exclusively by the kidney, should be characterized in preclinical animal models of sepsis and within patient populations to determine if it may have a potential therapeutic benefit as well." (PMID 35163625, 2022). "This is in contrast to both a preclinical model of ischemia reperfusion injury AKI and a patient population with AKI in which circulating uromodulin is acutely depleted, suggesting that the kidney damage in CLP sepsis is not sufficient to deplete circulating uromodulin." (PMID 35163625, 2022).
Ureteral obstruction (2 papers, 2018 to 2020). Obstruction of the flow of urine through the ureter. "This study investigated whether UMOD deficiency modified responses to unilateral ureteral obstruction (UUO)‐induced kidney injury." (PMID 29595914, 2018).
anemia (1 paper, 2013). A reduction in the number of red blood cells, the amount of hemoglobin, and/or the volume of packed red blood cells. "The patients were comprehensively investigated for common etiologies of anemia, uric acid metabolism and mitochondrial metabolism, including sequencing of several genes (HNF1, UMOD, CoQ2, PDSS2 and partially the mtDNA) but no underlying cause was identified." (PMID 24034276, 2013).
bacteremia (1 paper, 2015). "We did however observe that the inability to produce uromodulin in the urine greatly increased the risk of developing bacteremia (OR 6.0, 95% CI: 1.2–29.2)." (PMID 25807366, 2015). "Whether uromodulin lowers the risk for developing febrile UTI or associated bacteremia is unknown." (PMID 25807366, 2015). "We did find a risk factor, lack of uromodulin, that is present in few patients but greatly increases their risk of developing bacteremia." (PMID 25807366, 2015). "We did find that while uromodulin production is in general not different between patients and controls, complete absence of uromodulin production in the urine is a strong risk factor for bacteremia." (PMID 25807366, 2015). "Lack of uromodulin production in the urine appears to be a valuable biomarker for bacteremia in vulnerable UTI patients." (PMID 25807366, 2015). "The odds ratio for developing bacteremia for UTI patients who do not produce uromodulin is 6.0 (95% CI: 1.2–29.2)." (PMID 25807366, 2015). "Of the 16 individuals who did not produce detectable uromodulin only a few had a condition that affected the kidneys: two patients with bacteremia had chronic kidney insufficiency and one other had urothelial cell carcinoma." (PMID 25807366, 2015). "Most people produce uromodulin in the urine regardless of infection and it appears that inability to produce any uromodulin is more common in the patients with bacteremia than in patients without bacteremia (p = 0.015)." (PMID 25807366, 2015). "Uromodulin was detectable in 78 of all 89 (88%) UTI patients, in 42 of 44 (95%) without bacteremia and in 35 of 45 (78%) with bacteremia, and in 42 of the 46 (91%) controls." (PMID 25807366, 2015). "The median value of the controls is 2366 ng uromodulin /μmol creatinine, of the UTI patients without bacteremia it is 1941 ng/μmol and of those with bacteremia 1851 ng/μmol." (PMID 25807366, 2015).
E. coli infection (1 paper, 2009). "Third, uromodulin may be a defensive factor in the urinary tract against uropathogenic E. coli infection stimulated by high concentrations of mannose residues." (PMID 19529781, 2009).
focal segmental glomerulosclerosis (1 paper, 2022). A renal disorder characterized by sclerotic lesions in the glomeruli. "Disease-causing autosomal dominant rare UMOD mutations C315F, W202S, and C106F are reported in families with focal segmental glomerulosclerosis (FSGS) or hereditary glomerular disease, thereby linking uromodulin function to broader renal function regulation." (PMID 36140271, 2022).
frontotemporal dementia (1 paper, 2022). Frontotemporal dementia (FTD) comprises a group of neurodegenerative disorders, characterized by progressive changes in behavior, executive dysfunction and language impairment, as a result of degeneration of the medial prefrontal and frontoinsular cortices. "Of interest, urinary uromodulin has been suggested as a potential biomarker for cognitive ability in old age, and a recent serum analysis in patients with frontotemporal dementia found that serum uromodulin, among other proteins, was dysregulated in patients compared to controls." (PMID 34593962, 2022).
glomerulosclerosis (1 paper, 2023). A hardening of the kidney glomerulus caused by scarring of the blood vessels. "In a study on 364 patients who underwent kidney biopsies, urinary uromodulin levels were negatively associated with serum creatinine and patients with higher uromodulin levels had lower degrees of kidney fibrosis and glomerulosclerosis." (PMID 37298105, 2023).
Hematuria (1 paper, 2012). The presence of blood in the urine. "The value of the IgA–uromodulin complex tends to be higher not in inactive IgAN having no hematuria but in the earlier phase of the disease in which inflammatory activity is still active." (PMID 22415778, 2012).
Hyperkalemia (1 paper, 2025). An abnormally increased potassium concentration in the blood. "This difference was not correlated with hyperkalemia or the blood potassium levels, suggesting a sex-dependent role of uromodulin in stone formation." (PMID 40559466, 2025).
ischemic stroke (1 paper, 2021). A stroke disorder caused by obstruction of blood flow to the brain, due to thrombotic (local blood clot formation) or embolic (due to a blood clot or other material traveling from another site) event. "Further analyses of clinical data are needed to understand the role of uromodulin after ischemic stroke." (PMID 33768217, 2021). "Further analyses are needed to understand the role of uromodulin following ischemic stroke." (PMID 33768217, 2021). "The increase in uromodulin in people with high BMI could be a protective reaction of the kidney to worsening conditions that make ischemic stroke more likely, with a goal of delaying dangerous outcomes." (PMID 33768217, 2021).
leptospirosis (1 paper, 2024). A contagious bacterial infection caused by spirochetes of the genus Leptospira. "Sea lions with leptospirosis also showed a lower level of uromodulin in their urine." (PMID 39061561, 2024).
liver cirrhosis (1 paper, 2023). "Moreover, similar results were observed when examining serum uromodulin in a study involving patients with liver cirrhosis, where the admission level of serum uromodulin demonstrated an inverse relationship with the incidence of AKI during hospitalization." (PMID 37835820, 2023).
malaria (1 paper, 2025). Malaria is a serious and sometimes fatal disease caused by a parasite that commonly infects a certain type of mosquito which feeds on humans. "UMOD itself was differentially expressed in 'amakihi experimentally infected with malaria via the bite of an infectious mosquito versus subinoculation of infected blood, but not in other comparisons." (PMID 40909016, 2025).
minimal change glomerulopathy (1 paper, 2024). "Differences in urinary abundance in alpha-1-antitrypsin and uromodulin have previously been suggested for distinction between minimal change glomerulopathy (MCGN) and FSGS disregarding the different subcategories of FSGS." (PMID 38313685, 2024).
obstructive uropathy (1 paper, 2023). "While uromodulin is not directly implicated in the pathogenesis of tissue injury in obstructive uropathy, it serves as a valuable marker for detecting urinary extravasation and delineating the altered pathways of urine flow within the kidney during pathological conditions." (PMID 37835820, 2023). "In a rat model of unilateral obstructive uropathy, urinary casts containing uromodulin were identified not only downstream from the location of the uromodulin synthesis within the cells of the ascending limbs of the loop of Henle, but also at other points along the urinary tract." (PMID 37835820, 2023).
pancreatic cancer (1 paper, 2021). "We hope that its robust genetic associations with pancreatic cancer, coupled with its emerging role in gastrointestinal mucosal immunity, will spur renewed research interest in GP2, which has been understudied over the past 30 years compared with its paralog uromodulin (UMOD)." (PMID 34861888, 2021).
pregnancy hypertension (1 paper, 2024). "Despite a wealth of studies showing an association of uromodulin with various cardiovascular diseases and kidney diseases outside of pregnancy, there has been little investigation of the association between urinary, or serum uromodulin and pregnancy hypertension and its outcomes." (PMID 38236469, 2024).
renal carcinoma (1 paper, 2019). A carcinoma arising from the epithelium of the renal parenchyma or the renal pelvis. "For example, 2 kidney-specific genes, UMOD and AQP2, were exclusively associated with the adjacent normal tissues from all 3 renal cancer types in training." (PMID 31026023, 2019).
renal hypoplasia (1 paper, 2014). Renal hypoplasia is a developmental anomaly in which one or both kidneys (unilateral or bilateral renal hypoplasia, respectively) have a deficit in the number of nephrons and may be small. "Studies into cases of ‘non-syndromic’ renal hypoplasia have identified mutations in several key genes which include PAX2, SIX2, BNP4, SALL1, UMOD and TCF2." (PMID 24886545, 2014).
rhabdomyolysis (1 paper, 2021). Necrosis or disintegration of skeletal muscle often followed by myoglobinuria. "As a second step, we reproduced these experiments by replacing uromodulin by myoglobin to mimic rhabdomyolysis." (PMID 34099830, 2021).
uremia (1 paper, 2023). A clinical syndrome associated with the retention of renal waste products or uremic toxins in the blood. "Albuminuria correlated with reduced urinary excretion of uromodulin, and a decrease in urinary uromodulin levels was linked to an eight-fold increased risk of cardiovascular death and uremia." (PMID 37835820, 2023).
urinary tract bacterial infections (1 paper, 2020). "Uromodulin (UMOD), also known as Tamm–Horsfall protein, is a kidney-specific protein, exclusively produced by the renal tubules, and it is involved in the control of water–electrolyte balance and in the defense against urinary tract bacterial infections." (PMID 33375198, 2020).
kidney disease (92 papers, 2010 to 2026). "Altered expression and structural changes in uromodulin have been implicated in a range of kidney disorders." (PMID 40519162, 2025). "Myh9&10 TAL-cKO mice develop progressive kidney disease along with altered expression and localization of UMOD and loss of NKCC2, consistent with TAL cell autonomous functions for MYH9&10." (PMID 39500539, 2025). "In the past two decades, Interest in UMOD was boosted by genetic studies that reported involvement of the UMOD gene, which encodes UMOD, in a spectrum of rare and common kidney diseases." (PMID 37322316, 2024). "UMOD is specifically produced in kidneys and is involved in a variety of diseases known as uromodulin-associated kidney disease." (PMID 36674778, 2023). "Missense mutations in the UMOD gene cause autosomal dominant tubulointerstitial disease, and single nucleotide polymorphisms of the UMOD gene are also associated with kidney disease." (PMID 37768810, 2023). "Genetic alterations comprising common low-effect to rare large-impact variants of kidney disease genes such as UMOD or MUC1 determine the susceptibility to the development of CKD." (PMID 37316299, 2023). "Future investigations into the roles of uromodulin and regulatory mechanisms are likely to yield even more profound implications for kidney disease diagnosis, risk assessment, and management." (PMID 37835820, 2023). "Genetic studies have already shown that variations in the UMOD gene can influence uromodulin production and function, potentially affecting susceptibility to kidney diseases." (PMID 37835820, 2023). "We characterized missense mutations associated with divergent severity of ADTKD‐UMOD as a first step to dissect properties of uromodulin mutants and pathways driving kidney disease." (PMID 37885358, 2023). "Recent studies have further validated this positive association between serum uromodulin levels and kidney function in populations with kidney diseases of different etiologies." (PMID 37835820, 2023). "UMOD gene mutations are implicated in uromodulin-associated kidney disease, while polymorphisms in the UMOD gene show a significant association with CKD." (PMID 37835820, 2023). "The association of uromodulin levels, polymorphisms, and mutations in conjunction with acute and chronic forms of kidney disease has been reported." (PMID 37768810, 2023). "Although poorly described in kidney disorders, this enzyme has been associated with alteration in uromodulin levels." (PMID 36465937, 2022). "Autosomal dominant tubulointerstitial kidney disease (ADTKD) is an important hereditary kidney disease, mainly caused by mutations of uromodulin (UMOD) or mucin-1 (MUC-1)." (PMID 36431026, 2022). "To date, two major studies have been performed to identify if the Uromodulin measured in blood is associated with nephropathy SLE." (PMID 36301848, 2022). "Rare mutations in UMOD cause one of the most common monogenic kidney diseases, autosomal-dominant tubulointerstitial kidney disease." (PMID 35446786, 2022). "UMOD is known to affect kidney function and mutations in that gene cause several syndromic kidney disorders." (PMID 31451708, 2019). "comprehensively reviewed the phenotype of 202 patients Uromodulin-associated kidney disease from 74 families, most of them were Caucasian." (PMID 29569962, 2018). "But the relationship between variants of UMOD and risk of kidney disease was complicated, the several rare mutation in UMOD gene has been described as a cause of uromodulin-associated kidney disease, an autosomal dominant disease." (PMID 27938332, 2016). "Uromodulin is exclusively produced in tubular cells in the thick ascending limb of Henle’s loop and increasingly found to be associated with kidney disease." (PMID 26257595, 2015). "Uromodulin-associated kidney disease (UAKD) is a rare dominant hereditary renal disease caused by amino acid-changing mutations in the uromodulin (UMOD) gene." (PMID 25409434, 2014).